CRP (C-reactive protein)
Diseases named in the same sentence as CRP in open-access papers (continued):
Sharing a sentence is not in itself a finding about the gene and the disease.
COVID-19 (continued). "cfDNA levels positively correlated with COVID-19 disease severity, C-reactive protein, and D-dimer." (PMID 33651717, 2021). "Consistent with this, a local case series from Pakistan identified age, presence of comorbidity, high neutrophil-to-lymphocyte ratio (NLR), LDH, and CRP levels as strong predictors of mortality among COVID-19 patients, which is also supported by other international studies." (PMID 34926030, 2021). "In addition, as a biomarker of disease progression in patients with severe COVID-19, the CRP/Alb ratio has the following advantages." (PMID 34900028, 2021). "Further, the coefficient plot revealed that the age > 65, nursing home, headache, dyspnea, AMS, consolidation, O2 saturation < 88, yno2, CAD, diabetes, alcohol, hypertension, stroke, dementia, prothrombin, and CRP were positively correlated with mortality among patients with COVID-19." (PMID 34496940, 2021). "Based on these data, our results suggest that the levels of the inflammatory biomarkers such as IL-6, CRP, and D-dimer might be related to the aggravation and deterioration of COVID-19, while lymphocytes might be used as a predictor of immune protection." (PMID 34712742, 2021). "Larger prospective studies are required to formulate a risk prediction tool for PE in COVID-19, which could incorporate a D-Dimer cutoff, respiratory rate, WCC, CRP and validated COVID-19 severity scores." (PMID 34319144, 2021). "Indeed, the plasma levels of interleukin-2 (IL2), interleukin-6 (IL-6), tumor necrosis factor α (TNFα), and C-reactive protein (CRP) are markedly elevated in COVID-19 patients." (PMID 34326911, 2021). "In addition, our findings show that CRP levels on admission were an early indicator for COVID-19 severity, which is consistent with recent publications." (PMID 33854695, 2021). "Additionally, acute-phase reactants (i.e., CRP, D-dimer, and ferritin) appeared to be similarly elevated in patients with COVID-19 and in patients with other inflammatory syndromes." (PMID 33669011, 2021). "A meta-analysis revealed that increased neutrophil-to-lymphocyte ratios and decreased lymphocyte-to-CRP ratios, which are two markers of systemic inflammation, were found in severe COVID-19 patients and may indicate a poor prognosis." (PMID 34593760, 2021). "For example, IL-6, CRP, and hypertension were ideal predictors for the progression of COVID-19, while older age, high Sequential Organ Failure Assessment (SOFA) score and D-dimer greater than 1 μg/L were risk factors for in-hospital death in COVID-19 patients." (PMID 33987176, 2021). "The results also indicated a positive correlation between CRP and COVID-19 severity in patients." (PMID 35154611, 2021). "Of note, many cases of T2DM with COVID-19 showed markedly increased CRP levels." (PMID 34447386, 2021). "We found increased CRP levels in severe cases of COVID-19 compared to mild ones." (PMID 33633875, 2021). "These two physiological effects of CRP apparently also occur in COVID-19." (PMID 33679775, 2021). "Due to the apparent fact that LAC values are very frequently found in COVID-19 patients, it should be noted that they can also be distorted by false positive measurements, especially in the case of an increase in CRP, which is also to be expected in severe COVID-19." (PMID 34259944, 2021). "Our retrospective analysis of the thyroid and lipid profile in COVID-19 patients proves that patients with SARS-CoV-2 infection develop hypolipidemia with reduced levels of LDL-C that negatively correlated with CRP and that TSH levels also appear to be reduced." (PMID 34440605, 2021). "We then evaluated whether exosomal protein cargo in COVID-19 patients significantly correlated with CRP and d-dimer levels, platelets, neutrophil, and monocytes counts." (PMID 33693030, 2021). "Some studies have reported that an elevated CRP is related to COVID-19 mortality." (PMID 33315348, 2021).
COVID-19 (continued). "Death form COVID-19 was associated with age (OR 1.06, 95% CI 1.02–1.10, P = 0.001), invasive ventilation (OR 37.12, 95% CI 13.36–103.14), COVID-19-related-neurological complications (OR 3.24, 95% CI 1.28–8.21, P = 0.01), and elevated CRP level (OR 1.01, 95% CI 1.00–1.01, P = 0.01)." (PMID 34566878, 2021). "Data from various clinical studies and meta-analyses confirmed the applicability of the infection-mediated clinical biomarkers IL-6, VEGF-D, SAA, CRP, serum ferritin, and PCT as prognostic and adjunct diagnostic indicators for developing electrical-based COVID-19 biosensors." (PMID 34205852, 2021). "However, debate remains over the utility of CRP as a prognostic marker for patients admitted to hospital with COVID-19." (PMID 33683344, 2021). "A study demonstrated that CRP and BMI were significantly higher in critical COVID-19 patients." (PMID 34867458, 2021). "Multivariate analysis revealed that influenza might associate with risk of elevated CRP, PCT, and LDH, whereas COVID-19 might associated with high HBDH." (PMID 34859002, 2021). "Increasing levels of selenium, and zinc in blood have been accompanied by a decrease in serum CRP level, inflammation, and severity of symptoms in COVID-19 patients, suggesting that supplementation with these micronutrients is pivotal to fight SARS-CoV-2 infection." (PMID 34829949, 2021). "In patients with moderate COVID-19, only Hs-CRP level was elevated." (PMID 33435865, 2021). "During the course of COVID-19, patients undergo some pathological changes (severe lymphopenia, high levels of C-reactive protein, D-dimer, ferritin, etc.)depending on the condition and exposure level of the affected systems as shown by various laboratory tests." (PMID 34445855, 2021). "Several lab tests such as IL-6, CRP and white blood cell subset counts may help predict the severity of COVID-19 during the patient’s hospital course if obtained when the patient first presents to the hospital." (PMID 34567235, 2021). "To provide a complete profile of inflammatory response during COVID-19, we evaluated prospective changes of general inflammatory markers, such as CRP, PCT, and ferritin, together with the different pro-and anti-inflammatory cytokines implicated in both innate and adaptive immunity." (PMID 33808205, 2021). "These patients may still be clinically suspected of COVID-19 infection, prompting either repeat PCR testing, performance of a full battery of COVID-19 blood tests (C-reactive protein, D-dimer, ferritin, troponin, etc.)to help further confirm COVID-19 status." (PMID 34125031, 2021). "Unfortunately, although the clinical features of COVID-19 patients have been reported in several recent publications, such as decreased lymphocytes and elevated CRP, the predictive powers and interpretations of these clinical features remain unclear." (PMID 34541519, 2021). "Early CRP levels in critical COVID-19 patients averaged 10.5 mg/dL." (PMID 34409491, 2021). "CRP levels were reduced in Dupilumab-prescribed patients with COVID-19, suggesting that blocking type 2 immunity may lower overall disease pathology and increase survival rates." (PMID 34185704, 2021). "On the other hand, association with the inflammatory mediators (ferritin, and in case of AST with CRP as well), may link these enzymes with the liver involvement in the inflammatory response to COVID-19." (PMID 34575333, 2021). "We found a nonsignificant association of CRP with hospitalization versus no hospitalization among people with COVID-19 (p = 0.002)." (PMID 33661905, 2021). "Furthermore, elevated CRP, D-dimer, and LDH levels as well as lymphopenia have a significant association with the COVID-19 severity and can be used as valuable biomarkers to predict the disease severity." (PMID 33861750, 2021). "PCT and CRP measurement on admission and during the course of the disease in patients with COVID-19 may be helpful in identifying secondary bacterial infections and guiding the use of antibiotic therapy." (PMID 34021897, 2021).
COVID-19 (continued). "Currently, the effects of dexamethasone and tocilizumab on the kinetics of PCT and CRP in COVID-19 patients are unknown." (PMID 34353339, 2021). "The high levels of CRP could be due to the overproduction of inflammatory cytokines and tissue destruction in severe COVID-19." (PMID 35076497, 2021). "While there are many studies on CRP level in COVID-19 patients, studies on ferritin are limited." (PMID 33546639, 2021). "In terms of laboratory results, blood indices of COVID-19 patients were within the normal range on the admission, including peripheral white cell count, platelets, C-reactive protein, serum creatinine, aspartate transaminase, alanine transaminase, bilirubin, LDH, and creatine kinase." (PMID 34461841, 2021). "In this context, a study performed on 24 patients with COVID-19 found that exosomes derived from allogeneic bone marrow mesenchymal stem cells (Exo-MSC) are promising therapeutic candidates for severe COVID-19, by reducing the circulating CRP, ferritin and D-dimer." (PMID 34073119, 2021). "In summary, D-dimer, CRP, ferritin, cardiac troponin I, IL-6 are predictive laboratory markers and can largely determine the clinical course of COVID-19, in particular the prognosis of critically ill COVID-19 patients." (PMID 34262116, 2021). "CRP levels also correlate with CT findings of COVID-19 patients." (PMID 33679775, 2021). "In this cohort study of adult patients hospitalized with COVID-19, we found that patients who had a history of VTE, peak D-dimer greater than 3 μg/mL, and predischarge CRP greater than 10 mg/dL were at high risk of experiencing new onset of VTE after discharge from hospital." (PMID 34807256, 2021). "In our study, the subjects with mild COVID-19 demonstrated normal CRP levels." (PMID 34888326, 2021). "Above all, this study proposed a simple and clinically operable decision tree model to quickly quantify the risk of COVID-19 related death based on three biomarkers (LDH, NLR and CRP), which could be easily obtained on admission." (PMID 34372767, 2021). "The results showed that increased CRP, PCT, and LDH may associate with influenza (A and B) and increased HBDH with COVID-19." (PMID 34859002, 2021). "In conclusion, our findings highlight clinical features of patients infected with SARS-CoV2 and show that age ≥ 50 years, C-reactive protein levels and platelets count were independent prognostic factors of disease severity in COVID-19 patients aged ≤ 65 years." (PMID 33760885, 2021). "Indeed, NETs release has been associated with several clinical biomarkers, including acute-phase reactants (CRP and D-dimer) and inflammatory cytokines, in COVID-19 patients and is rendered a prognostic marker for diseases severity." (PMID 34960645, 2021). "In the acute COVID-19 group, HA correlated with all parameters except for CRP." (PMID 34635073, 2021). "The COVID-19 viral infection of some severe patients suffers from cytokine storm syndrome (CSS) causing hypotension, fever and high levels of C-reactive protein (CRP), abnormal coagulation, uncontrolled inflammatory response, shock and multiorgan system failure." (PMID 34751250, 2021). "Some modeling studies have shown that levels of IL-6 and CRP could be used as independent factors to predict the COVID-19 severity." (PMID 34960790, 2021). "CRP and ferritin were also useful biomarkers for predicting the disease severity of COVID-19." (PMID 34501223, 2021). "Prognostic score, a combination of variables like age, comorbidity, CD4+ T cell count, C-reactive protein (CRP), D-dimer, lactate dehydrogenase, cardiac troponin I, have been developed to predict the progression to severe illness and death in COVID-19 patients." (PMID 34844297, 2021). "Multivariate logistic regression analysis showed that lymphopenia, elevated level of d-dimer, hypersensitive cardiac troponin I (hs-CTnI) and high sensitivity C-reactive protein (hs-CRP) were independent predictors of mortality in young adults with severe COVID-19." (PMID 33407543, 2021).
COVID-19 (continued). "Interestingly, the CRP serum level had higher peaks in survivors than in those with the fatal course of COVID-19." (PMID 35011848, 2021). "RCT-TCZ-COVID-19 was conducted on a sample of 126 patients with pneumonia, PaO2/FiO2 between 200 and 300 mmHg and an inflammatory phenotype defined by fever and elevated CRP and also excluded patients requiring mechanical ventilation." (PMID 33679753, 2021). "In summary, the developed nomogram can be deployed for rapid and reliable mortality prediction of patients with both COVID-19 and non-COVID-19, based on multiple risk factors, such as Age, Lymphocyte count, D-dimer, CRP, and Creatinine." (PMID 34573923, 2021). "Multiple linear regression showed that COVID-19 status was associated with high plasma NEFAs, low HDL cholesterol levels and low ApoE plasma concentrations, independently from body mass index (BMI), SOFA score and plasma CRP." (PMID 34031519, 2021). "In line with this emerging understanding of the complex and multifactorial pathophysiology of COVID-19, we found that, unlike the levels of CRP and IL-6, IP-10 levels are associated with disease severity and reflect the patient’s response to corticosteroids." (PMID 33434221, 2021). "In accordance with our results, severe cases were found to have higher levels of antibody response and larger numbers of inflammatory cells and CRP levels in a study assessing the longitudinal dynamic changes in antibody responses against SARS-CoV-2 in 84 COVID-19 hospitalized patients." (PMID 34621457, 2021). "Patients with severe or critical COVID-19 usually display features of systemic inflammation, with increased levels of proinflammatory cytokines (interleukin (IL)-1 or IL-6) and other acute phase reactants (C-reactive protein (CRP), D-dimer or ferritin)." (PMID 35011938, 2021). "Lower levels of these cytokines and CRP are found in children with COVID-19." (PMID 33777864, 2021). "In contrast, the levels of CRP, D-dimer, and lactate were higher in COVID-19 patients." (PMID 33494706, 2021). "Next, we compared IP-10 accuracy for COVID-19 detection with other biomarkers widely recognized for identifying infection such as C reactive protein or procalcitonin as well as other parameters related to the COVID-19 disease such as D dimer, SpO2 and lymphocyte count." (PMID 34357148, 2021). "However, the levels of CRP, IL-6, and D–dimer in the severe COVID-19 group with hypertension were significantly elevated than in the normotensive severe COVID-19 group (P < 0.05)." (PMID 33869774, 2021). "CRP could also play a role in severely ill COVID-19 patients, since CRP levels in these patients are exceptionally high and severe tissue damage in the lungs will lead to ample binding of CRP." (PMID 34065953, 2021). "When infected by COVID-19, patients with underlying CVD were more likely to exhibit elevation of troponin T (TnT) levels, which was a high and markedly positive linear correlation with plasma high sensitivity CRP (hs-CRP) level." (PMID 34447386, 2021). "The discriminative capacity of CRP concentrations regarding COVID-19 was slightly lower than that of serum free thiol concentrations (AUC = 0.66, CI 0.51–0.81, p = 0.042) or CRP and serum free thiol concentrations combined (AUC = 0.68, CI 0.53–0.83, p = 0.020)." (PMID 34943125, 2021). "The laboratory features in ICU and hospitalized COVID-19 patients may have increased CRP, ferritin, creatinine, urea, LDH, liver enzymes, lipase, D-dimer, and PT." (PMID 34650947, 2021). "To determine whether traditional biomarkers for inflammation showed the same elevated pattern with disease severity we measured IL-6 and CRP levels in COVID-19 patients across hospital settings." (PMID 33816549, 2021). "Furthermore, immunomodulatory treatment with dexamethasone and tocilizumab considerably reduces the value of PCT and CRP for detection of secondary infections in COVID-19 patients." (PMID 34353339, 2021).
COVID-19 (continued). "The possible correlation with elevated fibrinogen and CRP (C-reactive protein) with hypercoagulability may lead to stroke in patients with severe COVID-19." (PMID 34683488, 2021). "Another study reported eosinopenia (<0.02 109/L) alone or in combination with elevated high-sensitivity C-reactive protein (≥4 mg/L) could be used for separating the two groups and thus providing a biomarker with predictive capacity for diagnosing COVID-19." (PMID 33946171, 2021). "This successful treatment of a fulminant COVID-19 course with poor prognosis indicates that the use of CRP apheresis should be considered a therapeutic option in moderate to severe COVID-19 courses with a pronounced increase in CRP plasma levels." (PMID 34408751, 2021). "Furthermore, the prognostic value of the CRP in the progression of COVID-19 cases has been revealed." (PMID 33968148, 2021). "The induced decision trees confirm the importance of LDH and WBC counts in the decision-making process across Groups A, C, and D. Furthermore, the decision trees have highlighted the importance of CRP and number of lymphocytes as prominent factors for mortality in COVID-19." (PMID 35054223, 2021). "People living with HIV with suppressed viral loads who are hospitalized with COVID-19 have similar levels of CRP, IL-6, ferritin and neutrophil counts as HIV-negative individuals, though these laboratory values were lower in people living with HIV without suppressed viral loads." (PMID 34567235, 2021). "Finally, we evaluated changes in angiotensin II, IL-6, and CRP levels in four patients who were administered ARBs to determine the change of angiotensin II due to ARBs in COVID-19 patients." (PMID 34285712, 2021). "High CRP levels can also be used for early diagnosis of severe pneumonia in COVID-19 patients." (PMID 34538093, 2021). "We isolated platelets from naïve healthy donors, incubated them with plasma from COVID-19 patients (day 0, no anti-platelet medication) and analyzed platelet activation in response to cross-linked collagen-related peptide (CRP-XL)." (PMID 34957266, 2021). "Notably, increasing serum CRP levels corresponded to disease progression, serving as an early predictor for COVID-19 complication, prior to indications of critical findings with CT scan." (PMID 33628256, 2021). "We then compared the performance characteristic of progranulin as a biologic marker for the differentiation between sepsis, the systemic inflammatory response to major surgery, bacterial pneumonia and COVID-19 to that of the established indicators procalcitonin, interleukin-6 and C-reactive protein." (PMID 34476621, 2021). "Many reports observed a significant increment in CRP levels in COVID-19 patients compared to normal individuals, furthermore, higher CRP levels were found in the majority of COVID‐19 patients presented with severe illness compared to mild or non‐severe patients." (PMID 34855832, 2021). "Both the absolute CRP concentration and the trajectory during the first week of hospital admission are important factors predicting microbiology culture positivity and outcome in patients hospitalised with COVID-19." (PMID 34496795, 2021). "Besides, the results of Pearson correlation analysis showed that serum LDL-C levels of COVID-19 patients was negatively correlated with CRP level." (PMID 34124081, 2021). "Also, ginger improved clinical symptom recovery rate (tiredness, dry cough, fever), and paraclinical features (C-reactive protein, lymphocytopenia, and thrombocytopenia,) of patients with severe acute respiratory syndrome due to COVID-19 within seven days." (PMID 34014936, 2021). "IL-6 and CRP were the strongest predictors of severity in hospitalized patients with COVID-19." (PMID 33305624, 2021). "Modeling COVID-19 progression through DBNs by cytokines’ measurements over time identified notable dependencies among clinical and biological markers, where most of them are biomarkers of inflammation, including the IL-8, IL-6, CRP, LDH, and TNF." (PMID 35054223, 2021).